MMP9 (matrix metallopeptidase 9)
Diseases named in the same sentence as MMP9 in open-access papers (continued):
Sharing a sentence is not in itself a finding about the gene and the disease.
ovarian carcinoma (continued). "Moreover, Rg3-induced downregulation of MMP9 is associated with the decreased invasive capacity of ovarian cancer cells." (PMID 32733585, 2020). "Increased expression of MMP-9 is associated with poor prognosis in ovarian cancer." (PMID 28538838, 2017). "MMP9 has been implicated in invasion and metastasis in ovarian cancer." (PMID 27074576, 2016). "With regard to ovarian cancer, the expression of MMP-9 has been linked with invasive subtypes." (PMID 26539720, 2015). "However, in ovarian cancer, tumor MMP-9 expression is associated with longer survival, whereas stromal MMP-9 expression is associated with shorter survival." (PMID 25888323, 2015). "Furthermore, circulating levels of VEGF and MMP-9 have been reported to be strongly associated with angiogenesis and ovarian cancer prognosis." (PMID 20334653, 2010). "Matrix metalloproteinase-9 (MMP9), an extracellular endopeptidase, is upregulated by Epidermal Growth Factor (EGF) signaling and associated with ovarian epithelial cancer progression." (PMID 41732872, 2026). "Propofol inhibits the cell viability, migration and invasion, and induces apoptosis, which is related to the upregulation of miR-9 expression and the inhibition of NF-κB and MMP-9 expression in ovarian cancer cells." (PMID 40309242, 2025). "Several studies have shown the upregulation of MMPs, such as MMP2 and MMP9, in ovarian cancer tissues compared to normal or benign ovarian tissues, and their expression levels correlate with clinical stage, tumor invasiveness, and metastatic potential." (PMID 40558552, 2025). "Inhibition of CRM1-mediated nuclear export has been demonstrated to enhance the accumulation of mTOR in the nucleus, resulting in decreased protein levels of mTOR and its downstream targets, STAT3 and MMP9, in ovarian cancer cells." (PMID 41578763, 2025). "Expression levels of matrix metalloproteinase-2 (MMP-2) and MMP-9 can be utilized as biomarkers to assess the metastatic potential of ovarian cancer and the invasiveness of breast cancer cells." (PMID 40140925, 2025). "Our own data indicate the significant expression of MMP9 on the surface of sEVs and exosomes in patients with ovarian cancer and borderline ovarian tumors (plasma and ascites vesicles), as well as in patients with colon polyps and colorectal cancer." (PMID 39996852, 2025). "In previous studies, we also found that TMEFF1 promotes the expression of N-cadherin, Vimentin, MMP2, and MMP9 in ovarian cancer cells, inhibits the expression of E-cadherin, and participates in the EMT process." (PMID 38468232, 2024). "Among gelatinases, MMP2 expression was downregulated, while the MMP9 level was significantly higher in ovarian cancer." (PMID 38397798, 2024). "The roles of Lgals9, MMP9, and E-cadherin in epithelial ovarian cancer were investigated by immunohistochemical assays and qRT-PCR detection." (PMID 38992056, 2024). "The different combinations of the urine levels of two metalloproteinases (MMP-2 and MMP-9) and MMP-9/neutrophil gelatinase-associated lipocalin (NGAL) complex and age were evaluated in ovarian cancer compared to benign tumors." (PMID 38275400, 2024). "Conversely, down-regulating MMP2 and MMP9 has been shown to reduce metastasis and migration in retinoblastoma, bladder, oral, and ovarian cancer cells." (PMID 40066127, 2024). "In a similar study, auraptene, a natural coumarin mainly obtained from Citrus spp., was shown by gel zymography to dose-dependently inhibit the activities of both MMP-2 and MMP-9 in both human ovarian cancer (A2780) and cervical cancer (HeLa) cell lines." (PMID 39364049, 2024). "This elevation in hormone levels can stimulate the production of MMP-9 by TAMs, creating a favorable environment for angiogenesis, invasion, and the production of VEGF, IL-6, and MMP-9 in patients with ovarian cancer and lung adenocarcinoma." (PMID 38254696, 2024). "The treatment of ovarian cancer cells with 1,25(OH)2D3 decreased the expression of MMP-9 in M2 macrophages." (PMID 38069361, 2023).
ovarian carcinoma (continued). "MMP9, a 92-kDa type IV collagenase, was highly expressed in patients with advanced ovarian cancer and correlated with poor prognosis." (PMID 38203692, 2023). "They showed increased MMP-9 expression was related with a worse outcome in ovarian cancer patients (HR = 1.68, 95 percent CI 1.09–2.59, p = 0.02)." (PMID 37833873, 2023). "Thereafter, a number of regulated proteins in the downstream signaling pathway of EGFR were identified by examining the mechanism through which MICALL2 induced MMP9 transcription in ovarian cancer cells." (PMID 38203692, 2023). "The increased expression and activity of MMP7 and MMP9 create conditions favorable for the metastasis of ovarian cancer cells by remodeling the extracellular matrix, enhancing their migration, and facilitating attachment to secondary sites." (PMID 37569592, 2023). "CircATRNL1 absorbs miR-378, activates Smad4, and further decreases the activities of Akt, Cyclin D1, MMP2 and MMP9, thereby inhibiting proliferation, angiogenesis and metastasis of ovarian cancer cells." (PMID 37940982, 2023). "These processes result in the upregulation of MMP9 expression, which stimulates invadopodia formation and ovarian cancer cell invasion." (PMID 38203692, 2023). "Matrix metalloproteinase (MMP)-2 and MMP-9 play important roles in various steps of metastasis in human ovarian cancer cells." (PMID 37507925, 2023). "The present study investigated the effect of DNC, Oxa, and combination treatments of these two agents on the mRNA and protein expression levels of MMP-2 and MMP-9, as two documented MMPs correlated with ovarian cancer progression." (PMID 36658640, 2023). "In the present work, the elimination of ZNF252P-AS1 exhibited decreased expression of MMP2 and MMP9 in ovarian cancer." (PMID 34980214, 2022). "The expression of N-cadherin, vimentin, MMP2 and MMP9 was significantly reduced when ZNF252P-AS1 was inhibited in ovarian cancer cells, whereas E-cadherin was dramatically up-regulated." (PMID 34980214, 2022). "This proteoglycan, in turn, promotes the motility and invasion of ovarian cancer cells by a mechanism involving activation of the NF-κB signaling pathway and overexpression of matrix metalloproteinase-9 (MMP9) and CD44." (PMID 35454809, 2022). "Our results showed that the levels of heparinase 1, MMP9, β-catenin, and N-cadherin were significantly downregulated in ovarian cancer cells in response to Gleditsiae Spina treatment in a dose-dependent manner." (PMID 35299895, 2022). "quantified levels of two metalloproteinases (MMP-2 and MMP-9) and neutrophil gelatinase-associated lipocalin (NGAL) in urine samples collected from women with ovarian cancer and healthy controls." (PMID 35166350, 2022). "Here, we found that GOLM1 knockdown significantly reduced VEGF and MMP-9 expression compared with scramble knockdown group; on the contrary, GOLM1 overexpression significantly upregulated VEGF and MMP-9 expression in ovarian cancer cells." (PMID 35116068, 2022). "In ovarian cancer, VEGF-A has been linked to VM formation by elevating the expression of MMP-9, MMP-2, VE-cadherin, and EphA2." (PMID 35747793, 2022). "Recent studies have demonstrated certain anticancer strategies to inhibit the expression of pro-invasive factors, MMP2 and MMP9, in ovarian cancer using natural compounds." (PMID 35621926, 2022). "The positive correlation between HK2 and p-Akt1 (r = 0.4979, p = 0.0105), fibronectin (r = 0.1850, p = 0.0320) and MMP9 (r = 0.3821, p = 0.0020) in these human ovarian cancer tissues was confirmed by using Pearson correlation analysis." (PMID 35953860, 2022). "Among them, Sohlh2 was demonstrated to be an important inhibitor of ovarian cancer cell proliferation and metastasis by repressing the MMP9 expression." (PMID 35187167, 2022). "SLPI promotes ovarian cancer cell growth, prevents apoptosis in vitro and exerts a pro-metastatic function via increasing MMP-9 production in vivo." (PMID 36077500, 2022).
ovarian carcinoma (continued). "For example, MMP-9 expression was stimulated by cortisol and noradrenaline in macrophages from ovarian cancer patients." (PMID 36213817, 2022). "In that context, we have shown enhanced secretion of MMP-2 and MMP-9 in ovarian cancer cells cultured as spheroids compared to monolayer cultures." (PMID 36585738, 2022). "MMP2 and MMP9 are the members of matrix metalloproteinases family, which is closely related to poor prognosis in ovarian cancer patients." (PMID 34980214, 2022). "Together, these data indicate that CCL7 overproduction from macrophages stimulated by cancer cells increases the invasion of ovarian cancer cells by regulating MMP-9 via the ERK pathway." (PMID 34206004, 2021). "The high expression of CAMK2N1 and MMP9, on the other hand, has already been described in xenopatients of ovarian cancer treated with cisplatin." (PMID 33922695, 2021). "In this study, both ST09 treated ovarian cancer cell lines showed downregulation of MMP1, MMP2, and MMP9 with DDR1 loss." (PMID 34837026, 2021). "Upregulation of CXCR7 led to enhanced MMP-9 expression and cell adhesion and invasion in ovarian cancer." (PMID 34912809, 2021). "We conclude that the GSK3β/ETS1/MMP-9 axis regulates the biological aggressiveness of ovarian cancer." (PMID 34023818, 2021). "Elevations of matrix metalloproteinase (MMP)-9 in TAMs were detected in epithelial ovarian cancer tissue of patients with chronic stress." (PMID 34869378, 2021). "Subpopulation of MMP9+/MMP2+/EMMPRIN+ at the surface of blood plasma exosomes in high-volume ascites ovarian cancer patients was reduced compared to that in low-volume ascites patients." (PMID 33773551, 2021). "Upon generation of a specific antibody against phosphorylated ETS1, we demonstrated that phospho-ETS1 immunohistochemical expression in ovarian cancer specimens was correlated with that of MMP-9." (PMID 34023818, 2021). "Binding of the CXCR7 receptor to the ligand CXCL12 activates the p38 MAPK pathway to promote MMP-9 expression, thereby enhancing ovarian cancer cell invasion." (PMID 33829065, 2021). "Isoflurane enhanced cell proliferation and migration via hypoxia inducible factor-1α (HIF-1α) and matrix metalloproteinase 9 (MMP9) in prostate and ovarian cancer cells." (PMID 33673181, 2021). "We have also reported previously an enhanced secretion of MMP-2 and MMP-9 by floating ovarian cancer spheroids, with diminished expression of several integrins." (PMID 35047406, 2021). "It was reported that blocking Snail expression inhibited the activity of MMP-9 in ovarian cancer cells." (PMID 31956363, 2020). "We previously developed plasma-activated medium (PAM) for clinical use, and demonstrated that PAM exhibits a metastasis-inhibitory effect on ovarian cancer through reduced MMP-9 secretion." (PMID 32005941, 2020). "Although there is a difficulty that normal tissue expresses a little of MMP9, the mouse model results predicted that this probe can help identify human ovarian cancer up to five months earlier than current biomarker detections." (PMID 32377504, 2020). "For instance, the ligation of integrin to collagen in ovarian carcinoma cells resulted in the downregulation of E-cadherin through MMP9." (PMID 32906721, 2020). "CCL5 mediates invasiveness by activating NF-kB and increasing the secretion of MMP-9, both up-regulated in ovarian carcinoma stem-like cells and also in primary tumors." (PMID 32630699, 2020). "Our immunoblot analysis revealed decreased expression levels of MMP‐2 and MMP‐9 in UGDH‐silenced ovarian cancer cells, which is consistent with previous reports." (PMID 32893977, 2020). "SLPI was increased in ovarian cancer and enhances the invasiveness of ovarian cancer cells via modulating MMP-9 release." (PMID 32742768, 2020).
ovarian carcinoma (continued). "For example, up-regulation of RASSF5 expression can inhibit the growth of OC cells, over-expression of FZD3 can increase the survival time of OC patients, and inhibition of MMP9 gene expression can block metastasis of ovarian cancer cells." (PMID 31182053, 2019). "Matrix metalloproteinase-9 (MMP-9) has been implicated in the progression and metastasis of various cancers, such as cervical cancer, and ovarian carcinoma." (PMID 31293204, 2019). "In our study, we found that HE4 knockdown inhibited the expression of MMP-2 and MMP-9 in ovarian cancer cells." (PMID 31477564, 2019). "MMP-9 is expressed by primary ovarian carcinoma cells derived from the ovary, metastatic implants and ascites." (PMID 29393911, 2018). "Studies of human epithelial ovarian cancer (EOC) suggest that overexpression of MMP9 in ovarian cancer stroma is a significant predictor of shortened disease-specific survival." (PMID 29581841, 2018). "Both MMP-2 and MMP-9 were enhanced in one of the ovarian cancer cell lines (SKOV3) in response to gonadotropins, while TIMP-1 and TIMP-2 were down regulated, suggesting an inverse relationship between MMPs and their endogenous inhibitors." (PMID 29393911, 2018). "Degradation of FBLN5 would thereby increase MMP-9 protease activity or facilitate ovarian cancer cell adhesion to matrix substrates." (PMID 29581841, 2018). "MMP2 and MMP9 have also been reported to be correlated with poor survival in ovarian cancer patients and promoted ovarian cancer cell invasion." (PMID 30453504, 2018). "Compared with MMP9(+/+) mice, MMP9(−/−) animals implanted with human ovarian cancer cells have decreased microvessel density and macrophage infiltration into the lesions." (PMID 28929459, 2018). "Matrix metalloproteinases (MMPs), especially MMP-2 and MMP-9, are proteases that are capable of degrading the extracellular matrix to support cancer cell escape from the primary tumor site and metastasis in ovarian cancer." (PMID 29221185, 2017). "In ovarian cancer tissues and cultivated ovarian cancer cells, elevated αvβ6 expression is associated with the secretion of urokinase-type plasminogen activator (uPA), MMP-2, and MMP-9." (PMID 28869579, 2017). "MMPs are correlated with ovarian cancer, with the levels of MMP-2, MMP-7 and MMP-9 elevated in ovarian cancer patients." (PMID 28957437, 2017). "Here, we demonstrate, for the very first time, constitutive activation of STAT3 in ovarian cancer cells, and that MMP-9 gene promoter contains a STAT3 DNA responsive element." (PMID 28859117, 2017). "MMP-9, a marker of cell invasion, has been found to increase tumor growth and metastasis in ovarian cancer." (PMID 29050292, 2017). "In this study, we first determined the abundance of STAT3, p-STAT3, and MMP-9 in ovarian cancer cells." (PMID 28859117, 2017). "Increased activity of MMP‐9 was observed in both the ovarian cancer cells, whereas MMP‐2 activity was increased only in PA‐1 cells, as shown by gelatin zymography." (PMID 28236660, 2017). "Filamin B (FLNB) suppresses the growth and metastasis of human ovarian cancer by down-regulating the activity of MMP-9 and secretion of vascular endothelial growth factor-A (VEGF-A)." (PMID 28538838, 2017). "As a previous study reported, MMP2 and MMP9 participate in the initiation of omentum metastasis in ovarian cancer." (PMID 29221185, 2017). "It has been shown that filamin B can suppress the growth and metastasis of human ovarian cancer by down-regulating the activity of MMP-9 and secretion of VEGF-A." (PMID 28538838, 2017). "For example, in invasive tumors like ovarian cancers, the transcriptional factor Snail and MMP9 expressions are closely connected since they have both been implicated in similar invasive processes." (PMID 27029067, 2016). "In ovarian cancer patients, MMP-9 serum levels were observed higher (64.87±12.82 ng/ml) vs control individuals' (51.13±7.78 ng/ml)." (PMID 27902750, 2016).
ovarian carcinoma (continued). "Metabolomic profiling showed everolimus significantly decreased the degradation products of collagen metabolites in tumor tissues and MMP9 expression in ovarian cancer cells, respectively." (PMID 26959121, 2016). "In the lungs of patients with oesophageal cancer, melanoma skin cancer, ovarian cancer etcetera, a high expression of MMP-9 was found which suggests that primary tumours can stimulate the production of MMP-9 in pre-metastatic areas." (PMID 26913068, 2016). "In vivo work using a murine model of ovarian cancer showed that chronic behavioural stress was associated with increased tumour growth and vascularisation and enhanced expression of VEGF, MMP-2 and MMP-9." (PMID 27899953, 2016). "In our study, we found that propofol upregulated miR-9 expression in ovarian cancer ES-2cells, by which it inhibited NF-κB activation and its downstream MMP-9 expression,leading to the inhibition of cell growth and invasion of ES-2 cells." (PMID 27982283, 2016). "The combined analysis of HB-EGF and MMP-9 actions indicated the presence of a feedback loop between HB-EGF induced production of MMP-9 in ovarian cancer cells and release of soluble HB-EGF from M2 macrophages that led to co-culture induced proliferation." (PMID 27888810, 2016). "Another study demonstrated that tumor samples from ovarian cancer patients with greater biobehavioral risk had higher levels of MMP2+ and MMP9+ macrophage populations." (PMID 25738355, 2015). "MMP2 and MMP9 have been previously reported to be direct target genes of miR-490-3p in ovarian cancer." (PMID 26714817, 2015). "We confirmed that the expression level of MMP-9 is correlated with the regulation of EphA2 during treatment for the ovarian cancer." (PMID 25788424, 2015). "ETS1 is found to be co-expressed with MMP-1 and MMP-9 in angiosarcoma of the skin, ovarial carcinoma cells and stromal fibroblasts in breast and ovarian cancer." (PMID 26177288, 2015). "For invasive tumors like ovarian cancers, Snail and MMP-9 expressions are closely connected since they have both been implicated in similar invasive processes." (PMID 26932374, 2014). "Mechanistically, Matrigel invasion assays and live cell imaging showed that gal-7 increased the invasive behavior of ovarian cancer cells by inducing MMP-9 and increasing cell motility." (PMID 25277199, 2014). "Quantitative RT-PCR analyses demonstrated that MMP-9 mRNA levels of most of the ovarian cancer cell lines were higher than that of control HOSE1C cells." (PMID 24533079, 2014). "Previous reports showed that poor prognosis of ovarian cancer patients correlates with overexpression of pro-MMP-9 and cyclin D1, whose expression is known to be regulated by NF-κB." (PMID 24533079, 2014). "In ovarian cancer tissues, MMP-9 mRNA expression was significantly up-regulated and Cyclin D1 mRNA levels tended to increase in ovarian cancer tissues although these mRNA expression in each sample did not correlate with NIK mRNA expression." (PMID 24533079, 2014). "The clinical value of using heparanase, as a prognostic biomarker, in combination with MMP-9 and Cathepsin, was reported for determining the extent of ovarian cancer metastasis before surgery." (PMID 25105093, 2014). "MMP-2 and MMP-9 degrade collagen IV, the major structural collagen of the basement membrane, and are suggested to be critical in the metastatic process of ovarian cancer." (PMID 23593315, 2013).